PCCB (propionyl-CoA carboxylase subunit beta)
Description:
This is one of the 2 subunits of the biotin-dependent propionyl-CoA carboxylase (PCC), a mitochondrial enzyme involved in the catabolism of odd chain fatty acids, branched-chain amino acids isoleucine, threonine, methionine, and valine and other metabolites. Propionyl-CoA carboxylase catalyzes the carboxylation of propionyl-CoA/propanoyl-CoA to D-methylmalonyl-CoA/(S)-methylmalonyl-CoA. Within the holoenzyme, the alpha subunit catalyzes the ATP-dependent carboxylation of the biotin carried by the biotin carboxyl carrier (BCC) domain, while the beta subunit then transfers the carboxyl group from carboxylated biotin to propionyl-CoA (By similarity). Propionyl-CoA carboxylase also significantly acts on butyryl-CoA/butanoyl-CoA, which is converted to ethylmalonyl-CoA/(2S)-ethylmalonyl-CoA at a much lower rate. Other alternative minor substrates include (2E)- butenoyl-CoA/crotonoyl-CoA (By similarity).
Tractability: Small molecule: a structure with a bound ligand is known. PROTAC: ubiquitination databases record sites on it; its protein half-life has been measured.
Gene: Protein-coding gene on chromosome 3 (136,250,314 to 136,337,896, forward strand). Ensembl gene ENSG00000114054.
Subcellular location: Mitochondrion matrix
Pathways (Reactome):
Metabolism: Biotin transport and metabolism; Propionyl-CoA catabolism
Disease: Defective HLCS causes multiple carboxylase deficiency
Metabolism of proteins: Mitochondrial protein degradation
Gene Ontology:
Molecular function: propionyl-CoA carboxylase activity; protein binding; ligase activity
Biological process: branched-chain amino acid metabolic process; fatty acid metabolic process; short-chain fatty acid catabolic process; fatty acid catabolic process
Cellular component: catalytic complex; mitochondrial matrix; mitochondrion; cytosol
Genetic constraint (gnomAD): Loss-of-function variants: 22 observed, 37.29 expected, observed/expected ratio (o/e) 0.59, 90% interval 0.42 to 0.84. The upper end of that interval is the gene's LOEUF score, 0.84, which puts it in group 3 of 6, group 1 being the genes least tolerant of losing a copy. Missense variants: 648 observed, 584.26 expected, observed/expected ratio (o/e) 1.11, 90% interval 1.04 to 1.18. Synonymous variants: 234 observed, 215.51 expected, observed/expected ratio (o/e) 1.09, 90% interval 0.98 to 1.21.
Gene-disease validity (ClinGen):
ClinGen rates the evidence that PCCB causes each of these diseases.
propionic acidemia (autosomal recessive): Definitive. An organic aciduria caused by the deficient activity of the propionyl Coenzyme A carboxylase and is characterized by life threatening episodes of metabolic decompensation, neurological dysfunction and that may be complicated by cardiomyopathy.
Homologues: Orthologues: chimpanzee PCCB (99% identical), dog PCCB (95% identical), guinea pig PCCB (95% identical), rabbit PCCB (95% identical), pig PCCB (94% identical), mouse Pccb (93% identical), rat Pccb (92% identical), macaque PCCB (88% identical), tropical clawed frog pccb (84% identical), zebrafish pccb (83% identical), Caenorhabditis elegans pccb-1 (73% identical), Drosophila melanogaster CG17177 (15% identical), and 1 more. Paralogues in human: MCCC2 (30% identical).
Diseases named in the same sentence as PCCB in open-access papers:
PCCB is named in the same sentence as 20 diseases in open-access papers, as found by Europe PMC text mining. Sharing a sentence is not in itself a finding about the gene and the disease. The quoted sentences say what the papers report.
propionic acidemia (13 papers, 2018 to 2025). "Propionic acidemia (PA) is a rare metabolic disorder caused by mutations in the propionyl-CoA carboxylase (PCC) gene (PCCA or PCCB), leading to reduced PCC activity and impaired propionyl-CoA metabolism." (PMID 40177291, 2025). "Propionic acidemia (PA) is a metabolic disorder caused by a deficiency of the mitochondrial enzyme propionyl‐CoA carboxylase (PCC) due to mutations in the PCCA or PCCB genes, which encode the two PCC subunits." (PMID 40302352, 2025). "PCCB deficiency causes propionic acidemia (PA), resulting in the accumulation of propionic acid metabolites, and dysfunction in the respiratory chain and urea cycle pathways." (PMID 39135799, 2024). "Propionic acidemia (PA) is a rare autosomal recessive disorder of metabolism caused by mutations in the PCCA or PCCB gene, leading to propionyl CoA carboxylase (PCC) enzyme deficiencies." (PMID 35296328, 2022). "Propionic acidemia (PA) (OMIM#606054) is a rare autosomal recessive disorder of metabolism caused by mutations in the PCCA or PCCB gene, which leads to deficiencies of the propionyl CoA carboxylase (PCC) enzymes." (PMID 35296328, 2022). "Propionic acidemia (PA) is a rare autosomal recessive metabolic disorder caused by mutations in the PCCA and PCCB genes, which encode subunits of the mitochondrial enzyme propionyl-CoA carboxylase (PCC)." (PMID 40044943, 2025). "Propionic acidemia (PA; MIM#606054) is a rare autosomal recessive metabolic disorder caused by mutations in the PCCA and PCCB genes." (PMID 40044943, 2025). "Propionic acidemia (PA) is an ultrarare disorder caused by deficiency of the mitochondrial enzyme, propionyl-CoA carboxylase (PCC), composed of PCCA and PCCB subunits." (PMID 36577040, 2023). "Propionic acidemia is a severe inherited metabolic disorder, caused by the deficiency of propionyl-CoA carboxylase which encoded by the PCCA and PCCB genes." (PMID 35331292, 2022). "Propionic acidemia (PA), one of the most frequent life-threatening organic acidemias, is caused by mutations in either the PCCA or PCCB genes encoding both subunits of the mitochondrial propionyl-CoA carboxylase (PCC) enzyme." (PMID 33503868, 2021). "Propionic acidemia (PA) is a severe monogenic disorder characterized by a deficiency of the mitochondrial protein propionyl-CoA carboxylase (PCC) enzyme, which is caused by mutations in the PCCA or PCCB gene." (PMID 33183246, 2020). "Propionic acidemia (PA)(OMIM#606054) is an inborn error of branched-chain amino acid metabolism, caused by defects in the propionyl-CoA carboxylase (PCC) enzyme which encoded by the PCCA and PCCB genes." (PMID 32819290, 2020).
schizophrenia (3 papers, 2021 to 2023). A major psychotic disorder characterized by abnormalities in the perception or expression of reality. "Here, authors prioritized Propionyl-CoA Carboxylase Subunit Beta (PCCB) as a schizophrenia-associated gene, and linked PCCB to GABAergic pathways using human forebrain organoids-based transcriptomic and metabolomic analysis." (PMID 37620341, 2023). "Meanwhile, based on our results, AS3MT, SFXN2, and PCCB may be potential biomarkers for preventing breast and thyroid cancers in patients diagnosed with schizophrenia." (PMID 36138824, 2022).
Alzheimer disease (1 paper, 2022). A progressive, neurodegenerative disease characterized by loss of function and death of nerve cells in several areas of the brain leading to loss of cognitive function such as memory and language. "Further validation was performed in another expression profile of AD, GSE33000, and the result implied high sensitivity and specificity of DGKG, MAP3K7IP2, NFKBIE, VIP, and PCCB for diagnosing Alzheimer’s disease (combined AUC = 0.9388)." (PMID 36092935, 2022).
breast carcinoma (1 paper, 2022). "Using TCGA gene expression data, we found that the AS3MT and PCCB genes were differentially expressed in breast cancer, and the expressions of SFXN2 and PCCB were significantly different in ovarian cancer." (PMID 36138824, 2022).
Chorea (1 paper, 2022). Chorea (Greek for 'dance') refers to widespread arrhythmic involuntary movements of a forcible, jerky and restless fashion. "For example, ‘childhood onset dystonia or chorea’ (PanelApp panel 847) is most frequently due to propionic acidemia, which in turn is caused exclusively by mutations in the PCCA and PCCB genes." (PMID 35456490, 2022).
Dystonia (1 paper, 2024). An abnormally increased muscular tone that causes fixed abnormal postures. "Our analysis also uncovered pathogenic or likely pathogenic variants in uncommonly dystonia-associated genes (PCCB, CACNA1A, ALDH5A1, PRKN) in four families where dystonia has been rarely observed in the spectrum of the clinical characteristics so far." (PMID 38458754, 2024). "Pathogenic or likely pathogenic variants were found in four families in genes that are not commonly associated with dystonia (PCCB, CACNA1A, ALDH5A1 and PRKN)." (PMID 38458754, 2024).
intellectual disabilities (1 paper, 2020). "Moreover, there were reports that patients carrying PCCB mutations exhibited intellectual disabilities." (PMID 32337102, 2020).
osteosarcoma (1 paper, 2022). A usually aggressive malignant bone-forming mesenchymal neoplasm, predominantly affecting adolescents and young adults. "As the most hazardous gene based on the stepwise multivariate Cox regression analysis, the biological function of PCCB in osteosarcoma was explored." (PMID 36531021, 2022). "As the most hazardous gene in the mitochondria-related signature, PCCB was found to mediate the proliferation of proliferation and migration of osteosarcoma cells." (PMID 36531021, 2022). "In contrast, T cell activation, B cell activation, and lymphocyte proliferation were highly enriched in osteosarcoma patients with low expression of PCCB." (PMID 36531021, 2022). "The IHC results further confirmed that the expression of PCCB was considerably higher in osteosarcoma tumor tissues than in normal tissues." (PMID 36531021, 2022). "PCCB was a potential oncogene in osteosarcoma, and the related complex regulatory mechanisms remain to be further explored." (PMID 36531021, 2022). "Besides, PCCB was found with significantly higher expression in osteosarcoma tumor tissues than in normal tissues." (PMID 36531021, 2022).
Sepsis (1 paper, 2025). Sepsis is defined as life-threatening organ dysfunction caused by a dysregulated host response to infection. "Our team found that the expression levels of ACADVL, AFG3L2, ETFB, PCCB, and PCK2 were significantly overexpressed in ARDS samples compared to sepsis samples (all P value < .05), which was consistent with the results of bioinformatics analysis." (PMID 40068062, 2025).
thyroid cancer (1 paper, 2022). "In breast and thyroid cancer, genes corresponding to the intersection sites (rs11191419, rs13240464, rs7432375) included SFXN2, AS3MT, IMMP2L, and PCCB." (PMID 36138824, 2022).
metabolic disorder (9 papers, 2020 to 2025). "PA is a rare metabolic disorder caused by mutations in PCCA or PCCB genes, resulting in impaired propionyl-CoA metabolism." (PMID 39975893, 2025). "However, in the rare disease known as propionic academia (PA)—a recessive metabolic disorder caused by mutations in the Propionyl-CoA Carboxylase Subunit Alpha (PCCA or PCCB genes)—impaired metabolism of propionyl-CoA leads to a variety of metabolic disorders." (PMID 40801563, 2025).
tumor (3 papers, 2022 to 2026). "Protein profiling identified ITH-associated proteins (WDR5, CKB, IPO11, ATP6V1F, DCXR and PCCB) and underscored pathway variations including tumour suppressor and proto-oncogenic signalling, vascularization and metabolic regulation." (PMID 41580526, 2026). "Our genome-wide screen study identified PCCB as a key regulator of anti-tumor T-cell activity." (PMID 40067762, 2025). "Both data revealed significantly lower PCCB expressions in tumor sections compared with adjacent normal tissues, which is consistent with our observation that low PCCB levels lead to tumor progression." (PMID 40067762, 2025). "However, PCCB’s role in cancer and whether it plays a role in the tumor immune response is completely unknown." (PMID 40067762, 2025).
genetic disease (1 paper, 2020). "Although there were no reports about the mechanism of PCCB function in neuron system development, mutations in PCCB are one of the major causes of the genetic disease propionic academia (PA)." (PMID 32337102, 2020).
PCCB also shares sentences with these, for which no sentence is quoted: cancer (2 papers); colon cancer (1); dyslipidemia (1); lung carcinoma (1); organic acidemias (1); ovarian carcinoma (1); pancreatic cancer (1).